CXCL12 (C-X-C motif chemokine ligand 12)
Diseases named in the same sentence as CXCL12 in open-access papers (continued):
Sharing a sentence is not in itself a finding about the gene and the disease.
leukemia (continued). "The essential roles of the CXCL12/CXCR4 axis in niche positioning and cell cycle status of leukemia stem cells have been highlighted by the specific deletion of CXCL12 from BM MSCs, suggesting the differential use of CXCL12-niches by CXCR4+ malignant cells." (PMID 34737747, 2021). "CXCL12 is the primary ligand for the chemokine receptor CXCR4, found on cell surface of HSCs and some leukemia cells." (PMID 35070954, 2021). "The CXCL12/CXCR4 pathway is involved in homing of T-ALL cells to the bone marrow and in Leukemia Initiating Cell (LIC) activity." (PMID 34394130, 2021). "Many chemokine axes such as CXCL12/CXCR4 and CCL25/CCR9 have been proved to play important roles in leukemia microenvironment and further affect ALL outcomes." (PMID 33743810, 2021). "Given that CXCR4D99G lacks the ability to bind to CXCL12, the results confirm that CXCL12 is dispensable for the growth and survival of MLL-AF9 leukemia cells." (PMID 32460032, 2020). "CXCL12/CXCR4 antagonists have shown encouraging results in reducing the enhanced survival and proliferation of leukemia cells and sensitizing leukemia cells to chemotherapy." (PMID 32660524, 2020). "The adipocyte stromal cell-derived factor 1-α (SDF-1α), also known as cysteine-X-cysteine (C-X-C) motif chemokine 12 (CXCL12), promoted leukemia cell migration into the adipose tissue." (PMID 33105727, 2020). "In human leukemia-derived cell lines and CD34+ hematopoietic progenitor cells, CXCL14 can compete with CXCL12 and thus inhibit CXCL12-CXCR4 signaling." (PMID 32708730, 2020). "CXCL12, BAFF, APRIL or a combination of all three significantly improved the viability of Eμ-Tcl1 Tg leukemias 5 days post ex vivo culture in comparison to medium alone and were effectively antagonized by GS-9820." (PMID 27843137, 2017). "Accordingly, both CXCL12 and CCL21 induced transmigration of Eμ-Tcl1 Tg leukemias in transwell assays." (PMID 27843137, 2017). "We identify that, in addition to the well-known CXCR4/CXCL12 axis, CCR2/CCL2 and CCR5/CCL4 also drive leukemia/stromal interactions." (PMID 26956049, 2016). "In case of CLL, the stromal factors such as SDF-1 (CXCL-12), BAFF, and APRIL play a major role in protection of the leukemia cells." (PMID 27655686, 2016). "Collectively, these results suggest that like CXCR4/CXCL12, the CCR2/CCL2 and CCR5/CCL4 receptor/chemokine axes contribute to leukemia-MSC interactions, and that the chemokines expressed by MSCs are regulated, at least in part, by ARC in AML cells." (PMID 26956049, 2016). "It is well established that interactions between the chemokine CXCL12, secreted by BM stromal cells, and its receptor CXCR4, expressed on the surface of leukemic cells, are very important for protecting leukemia cells from chemotherapeutic drugs." (PMID 27776559, 2016). "Third, understand how the CXCR4/CXCL12 axis is involved in tumor functions, such as how LSC homing and signaling transduction helped translate findings into additional clinical uses in leukemia and solid tumors." (PMID 27429863, 2015). "NOX-A12 spiegelmers specifically antagonize CXC chemokine ligand 12/stromal cell derived factor-1 (CXCL12/SDF-1), which is a key regulatory chemokine for migration of leukemia stem cells to the bone marrow." (PMID 25057429, 2013). "Taken into consideration limitations of the in vitro systems in the assessment of agents affecting tumor microenvironment, we evaluated the utility of combined blockade of CXCL12/CXCR4 and TGF-β signaling pathways in the in vivo leukemia model." (PMID 23826077, 2013). "A receptor antagonist Plerixafor is known to block active CXCL12/CXCR4 signaling in normal and leukemia stem cell." (PMID 23826077, 2013). "Additional constituents of BM niche, the stroma-secreted chemokine CXCL12 and its receptor CXCR4 play crucial roles in cell migration and stroma/leukemia cell interactions." (PMID 23826077, 2013).
leukemia (continued). "Stromal cells within bone marrow microenvironment constitutively secrete CXCL12 and the activation of CXCR4 induces leukemia cell migration to the marrow microenvironment, providing growth and drug resistance signals." (PMID 20049170, 2010). "We also performed a cell invasion assay using splenic leukemia cells of TCL1 Tg or ROR1xTCL1 dTg mice in response to mouse CXCL12, without or with stimulation of Wnt5a." (PMID 40295829, 2025). "The modified leukemic niche alters the expressions of cross-talk molecules (i.e., CXCL12 and JAG1) in MSCs to provide a distinct cross-talk between normal and leukemia cells, selectively suppressing normal primitive hematopoietic cells while supporting leukemogenesis and chemoresistance." (PMID 36865039, 2023). "In the leukemia microenvironment, all abnormalities indicate the presence of HIF-1 response, including the elevation of secretion of VEGF, C-X-C motif chemokine ligand 12 (CXCL12) and stem cell factor (SCF), hypoxia, and acidity." (PMID 35528614, 2022). "The transcriptional profiles of MSC reveal two characteristic signatures: a CXCL12-low inflammatory and leukemia expansion-like niche that likely supports leukemic burden and a CXCL11 high immune-suppressive and leukemia-initiating cell (SLIC)-like niche, where LICs are likely sustained." (PMID 35201533, 2022). "The leukemia cells in the EMI group showed abnormally low expression of miR-3677-5p but high expression of CXCL12 and CXCR4 mRNA, indicating that the miR-3677-5p/CXCL12 axis may be closely related to the occurrence of EMI in monocytic leukemia." (PMID 36569343, 2022). "The leukemia cells of M5 patients with EMI appeared to have low expression of miR-3677-5p and high expression of the mRNA of CXCL12 and CXCR4, which may be used as indicators of EMI and poor prognosis." (PMID 36569343, 2022). "Further, when control cells (shControl) were preincubated with CXCR4 antagonist (AMD3100), prior to the chemotaxis assay, CXCL12 was no longer able to induce leukemia cells migration." (PMID 33842460, 2021). "Neither leukemia cell line expresses significant amounts of CXCL12, thus CXCL12 secretion and autocrine signaling are not impacting this differential response." (PMID 35070954, 2021). "Therefore, as a future work the designing of leukemia animal models with employing recombinant CXC chemokines CXCL1, CXCL10 and CXCL12 is proposed for the examination of the role and ability of these chemokines in control of AML complications." (PMID 34711015, 2021). "The cellular populations and several molecular mechanisms involved in leukemic progression also often overlap, with mesenchymal lineage cells and endothelial cells being common targets of leukemia‐derived inflammatory signals (CCL3, TNF, CXCL12) identified across multiple leukemic subtypes." (PMID 34693187, 2021). "CXCL12 binds and activates its homologous receptor CXCR4 in the microenvironment of the bone marrow to mediate the transport of leukemia cells, while keeping in close contact with stromal cells and the extracellular matrix to generate growth-promoting and anti-apoptotic signals." (PMID 33381455, 2020). "As anticipated, leukemia cells expressing Cxcr4D99G or Cxcr4L251P did not respond to CXCL12 stimulation in culture, whereas Cxcr4WT-expressing cells responded." (PMID 32460032, 2020). "Furthermore, the interaction between stromal cell-derived factor-1 (SDF-1 or CXCL12) and chemokine receptor type 4 (CXCR4) is crucial for the migration and adhesion of leukemia cells to the bone marrow stroma." (PMID 32580317, 2020). "Taken together, our data suggest that CXCR4 signaling is essential for growth and survival of MLL-AF9 leukemia cells independent of CXCL12, MIF, and UBIQUITIN stimulation." (PMID 32460032, 2020). "Because we found that CXCL12 is dispensable for AML development, we next assessed whether UBIQUITIN or MIF promotes growth and survival of MLL-AF9 leukemia cells by binding to CXCR4." (PMID 32460032, 2020).
leukemia (continued). "While leukemia did not affect the number of mesenchymal stem/stromal cells (MSCs), PDGFRα+Sca-1+ (PαS) mesenchymal cells, CXCL-12 abundant reticular cells and vimentin+ fibroblasts, we observed significantly lower numbers of endothelial and osteoblastic cells." (PMID 29740160, 2018). "CXCL12/CXCR4 signaling axis promotes cell survival and proliferation and may contribute to the tropism of leukemia cells towards lymphoid tissues and bone marrow." (PMID 28526063, 2017). "The reason why decreased CXCL12 in the BM did not lead to a decreased number of leukemia cells is not known." (PMID 27481339, 2016). "The CXCR4 ligand (CXCL12) stimulates CXCR4 promoting cell survival and proliferation, and may contribute to the tropism of leukemia cells towards lymphoid tissues." (PMID 26646452, 2016). "Loss of normal hematopoiesis is a classical event during human myeloproliferative neoplasias and leukemias where the niche downregulate essential HSPC retention factors as CXCL12, SCF, LepR, Angpt1, Cdh2, Slit2, and TGF-β1 though pro-inflammatory factors secreted by leukemia-initiating cells." (PMID 28111575, 2016). "Given the reduced importance of CXCR4/CXCL12 in CML compared with normal HSCs, and CXCR4 antagonists are potential therapeutics for treatment of CML, the particular application that captures our attention is the recurrence of active leukemia." (PMID 27429863, 2015). "Bone marrow stroma can protect acute myeloid leukemia (AML) cells against chemotherapeutic agents and provide anti-apoptosis and chemoresistance signals through secreting chemokine CXCL12 to activate its receptor CXCR4 on AML cells, resulting in minimal residual leukemia and relapse." (PMID 26538086, 2015). "It is well known that CXCL12 secreted by non-malignant stromal cells recruits leukemia cells to bone marrow." (PMID 25312253, 2014). "Leukemia and lymphoma B cells express functional chemokine receptors including CXCR4 and are capable of directional migration (chemotaxis) by following gradients of chemokines such as SDF-1 (CXCL12), the ligand of CXCR4." (PMID 23460911, 2013). "Interestingly, both of our studies detected novel CXCL12-responsive AKT substrates, PDCD4 (pS457) and AKT1S1 (pT246), underscoring the potential role of AKT signaling and leukemias." (PMID 21949786, 2011). "Conditional ablation of Cxcl12 from perivascular stromal cells or OBLs demonstrated that HSCs occupy a perivascular but not an endosteal niche, whereas targeted deletion of Cxcl12 from BM stromal cells has allowed the identification of specialized niches supporting leukemia stem cell maintenance." (PMID 37045841, 2023). "As Src kinase family was described as a player in CXCL12/CXCR4 and PI3K or MAPK pathway in severe solid tumor, we hypothesized whether HCK could be a downstream target of CXCL12/CXCR4 pathway and contribute to the pathophysiology of leukemia cells." (PMID 33842460, 2021). "Indeed, targeting the CXCL12/CXCR4 axis appears to deliver the promising results in early-phase clinical trials, and it is expected that additional routes of interaction between leukemia and the BMM will be discovered." (PMID 32474572, 2020). "Therefore, we speculated that FLT3-ITD mutations potentiallyupregulate CXCR4 expression on the surface of leukemia cells and enhance the chemotaxis of AML cells toward CXCL12, consistent with previously reported results." (PMID 31434952, 2019). "Thus, the reasons why decreased CXCL12 expression in the BM did not lead to a decreased number of leukemia cell needs to be elucidated further." (PMID 27481339, 2016). "Indeed, direct leukemia-MSC contact via VCAM-1/VLA-4 interactions, together with CXCL12/CXCR4 signaling and inflammatory cytokine signaling, may contribute, to a different extent, based on space and time, to enhance leukemia survival by activating NF-kB signaling within the leukemic BM niche." (PMID 33922612, 2021).
leukemia (continued). "Although we did not observe a difference in the cycle status of leukemia cells upon disease development in Cxcl12−/− mice, given that CXCL12 keeps normal HSCs in a quiescent state, we speculate that CXCL12 also restrains cell cycle progression of AML cells at the early stages of AML development." (PMID 32460032, 2020). "This could explain why CXCL12 is dispensable for AML development in vivo, whereas in vitro, supra-physiological concentrations of CXCL12 promoted survival of leukemia cells in the absence of other cytokine stimuli." (PMID 32460032, 2020).
lung carcinoma (127 papers, 2009 to 2026). "The development of these effector functions of lung cancer has been linked to the function of the CXCR4/CXCL12 axis." (PMID 41383468, 2025). "CXCR4/CXCL12 interactions contributed to the promotion of tumor-initiating cells in lung cancer, which was associated with chemotherapy resistance." (PMID 38363409, 2024). "Immunohistochemical analysis revealed the expression of CXCL12 in different tumor histological types and variable degrees of CXCL12 expression in cancer cells and cancer-associated fibroblasts in lung cancer specimens." (PMID 37227446, 2023). "Analogously, lower expression level of CXCL12 is associated with improved survival and prolonged OS in esophagogastric, lung cancer and pancreatic ductal adenocarcinoma." (PMID 37564657, 2023). "Studies have reported that several chemokines, such as CCL2, CCL5, CCL4, CXCL19, and CXCL12, are associated with the progression, metastasis, and prognosis of lung cancer." (PMID 36118890, 2022). "The CXCR4 (chemokine)/CXCL12 (chemokine receptor) interaction helped to promote tumor-initiating cells in lung carcinomas, which was associated with resistance to chemotherapy." (PMID 34745015, 2021). "Our results indicated that the CXCL12 G801A polymorphism was associated with an increased risk of cancers, especially for breast and lung cancer." (PMID 25268356, 2014). "Metabolic analysis linked CXCL12 to inositol phosphate metabolism, and single-cell RNA sequencing from datasets GSE150321 and GSE127471 demonstrated that intermediate monocytes in lung cancer were highly active in this metabolic pathway." (PMID 41790655, 2026). "Estrogen has been demonstrated to increase CXCL12 expression by ER-positive tumors, including lung cancer, leading to proliferation and enhanced invasiveness of the tumor." (PMID 40589738, 2025). "Over the past years, the CXCR4/CXCL12 cascade has been a significant therapeutic target in lung cancer since it offers a major function in cancer development, metastasis, immunological evasion, and resistance to treatment." (PMID 41383468, 2025). "The chemokine CXCL12 along with its receptor, CXCR4, have been implicated in the progression and metastasis of cancers, including lung cancer." (PMID 40589738, 2025). "AMD3100 (plerixafor), a selective CXCR4 antagonist and disrupts the CXCR4/CXCL12 signaling and has shown antitumor activity in preclinical lung cancer models." (PMID 41383468, 2025). "This review systematically summarizes the biological functions and molecular mechanisms of the CCR9/CCL25 and CXCL12/CXCR4 axes in lung cancer." (PMID 40607416, 2025). "CXCL12 was identified as a key factor in NFs-to-CEFs conversion, with its expression positively correlated with CAFs markers in lung cancer." (PMID 40199862, 2025). "CXCR4 is known to direct lung cancer cells toward CXCL12-rich metastatic sites such as the bone marrow, liver, and brain, fueling metastatic dissemination." (PMID 41383468, 2025). "CXCL12 is additionally secreted by stromal fibroblasts, endothelial cells, and immune cells in lung cancer in such amounts that they form chemotactic gradients drawing CXCR4-expressing cancer cells to metastatic niches such as liver, brain, and bone marrow." (PMID 41383468, 2025). "Because CXCR4/CXCL12 constitutes a powerful therapeutic target to counter tumor progression, immune evasion, and therapy resistance, it plays a pivotal role in lung cancer." (PMID 41383468, 2025). "Conversely, miR-222, miR-127, miR-197, and miR-223 target C-X-C motif chemokine ligand 12 (CXCL12) and other associated genes, decreasing proliferation and impairing the tumor immune response in lung cancer, further enhancing dormancy." (PMID 39934876, 2025).